MTHFD2 (methylenetetrahydrofolate dehydrogenase (NADP+ dependent) 2, methenyltetrahydrofolate cyclohydrolase)
Diseases named in the same sentence as MTHFD2 in open-access papers (continued):
Sharing a sentence is not in itself a finding about the gene and the disease.
colon cancer (7 papers, 2013 to 2025). "In colon cancer cells, MTHFD2 downregulation also decreased cellular NADPH/NADP+ and GSH/GSSG ratios, disrupted redox homeostasis and increased cell toxicity upon hydrogen peroxide addition." (PMID 40604332, 2024). "Similarly, MTHFD2 knock-out colon cancer cells showed decreased NADPH and GSH levels and increased ROS levels upon cisplatin treatment." (PMID 40604332, 2024). "While the mechanism of MTHFD2 acetylation remains unknown, the upregulation of MTHFD2 deacetylation in the context of colon cancer supports the established role of increased MTHFD2 activity in cancerous cells." (PMID 37949226, 2023). "In rectal cancer compared to colon cancer, ABCC3, RFC‐1, and MTHFD2 expression was significantly lower, while TYMS expression was higher." (PMID 40357991, 2025). "The present study showed that the expression of ABCC3, MTHFD2, and RFC‐1 was lower, and TYMS higher, in rectal compared to colon cancer." (PMID 40357991, 2025). "In colon cancer, where SIRT3 is upregulated, decreased MTHFD2 acetylation results in MTHFD2 hyperactivation." (PMID 37949226, 2023). "Although MTHFD2 and SHMT2 were highly expressed in colon cancer cells, DHFR had a very low or undetectable expression in colon cancer cells." (PMID 29321536, 2018).
glioma (7 papers, 2017 to 2024). A benign or malignant brain and spinal cord tumor that arises from glial cells (astrocytes, oligodendrocytes, ependymal cells). "A bioinformatics analysis study showed that MTHFD2 was among the key genes that were downregulated in glioma and that such downregulation was associated with poor prognosis." (PMID 32411609, 2020). "According to the analysis, we found that only the downregulation of CDK17, GNA13, PHF21A, and MTHFD2 was closely associated with a decreased overall survival among patients with glioma." (PMID 29362722, 2017). "Survival analysis found that CDK17, GNA13, PHF21A, and MTHFD2 are closely associated with glioma." (PMID 29362722, 2017). "MTHFD2 can be targeted by miR-940 to inhibit glioma progression via inhibition of mitochondrial metabolism, and is highly expressed in GBM patients with a long survival time." (PMID 33193654, 2020). "In glioma, suppression of MTHFD2 through upregulation of miR-940 led to the disruption of intracellular 1C metabolism and exhibited anti-tumor effects." (PMID 32411609, 2020). "The causes and mechanisms behind the discrepant expression profiles and distinct prognostic values of MTHFD2 between glioma and other cancers remain elusive and deserve further investigations." (PMID 32411609, 2020). "In the expression level of human tumors, MTHFD2 is overexpressed in most cancer types, but exceptions are found in glioma, similar to our results." (PMID 29362722, 2017). "Up to now, the biological functions of CDK17, GNA13, PHF21A, and MTHFD2 in glioma have remained unclear." (PMID 29362722, 2017). "According to the study, downregulation of CDK17, GNA13, PHF21A, and MTHFD2 can be considered as biomarkers or therapeutic targets for glioma." (PMID 29362722, 2017). "Importantly, suppression of MTHFD2 and autophagy inhibition impaired glioma cells in glutamine-deprived conditions." (PMID 33468252, 2021). "The results suggested that CDK17, GNA13, PHF21A, and MTHFD2 might play important roles and potentially be valuable in the prognosis and treatment of glioma." (PMID 29362722, 2017).
gastric cancer (5 papers, 2007 to 2024). A primary or metastatic malignant neoplasm involving the stomach. "The influence of circ MTHFD2 and circPVT1 is also associated with a decrease in sensitivity to chemotherapy shown in gastric cancer." (PMID 36362406, 2022). "The association between miR-22 and MTHFR has also been reported in gastric cancer (GC), where the overexpression of miR-22 induced cancer proliferation by suppressing MTHFR and its mitochondrial isoform (MTHFD2)." (PMID 34209866, 2021). "We found that overexpression of MTHFD2, but not MTHFD1, is associated with reduced overall and disease-free survival in gastric cancer." (PMID 38723197, 2024).
kidney cancer (5 papers, 2013 to 2025). Primary or metastatic malignant neoplasm involving the kidney. "Moreover, MTHFD2 higher expression was associated with unfavorable prognoses in kidney cancer and pancreatic ductal adenocarcinoma." (PMID 38422037, 2024). "Comprehensive studies have indicated that MTHFD2 plays a significant role in cancer phenotypes, indicating consistent protein increase in various tumors, including breast, colon, liver, and kidney cancers." (PMID 38422037, 2024). "MTHFD2 and HIF2A appear to form a positive feedback loop in kidney cancer, where MTHFD2 stabilizes HIF2A but is also a transcriptional target of HIF2A, as HIF2A promotes MTHFD2 expression by binding to its promoter." (PMID 40604332, 2024).
pancreatic cancer (5 papers, 2021 to 2023). "MTHFD2 expression is highly upregulated in a variety of cancers and is an independent prognostic indicator in breast and pancreatic cancer." (PMID 37986788, 2023). "We searched for genes, whose mRNAs are correlated with MTHFD2 not only in cancer cells from RNA-seq but also in pancreatic cancer clinical samples from the TCGA database." (PMID 33782411, 2021). "Consistently, the O-GlcNAcylation level positively correlates with MTHFD2 and PD-L1 in pancreatic cancer patients." (PMID 33782411, 2021). "IHC was performed to semi-quantify the MTHFD2, O-GlcNAc, and PD-L1 levels in 73 consecutive human pancreatic tumor specimens." (PMID 33782411, 2021). "MTHFD2 is overexpressed in some tumors and has been shown to contribute to the development of cancer stem cells and is considered a poor prognostic factor in several tumors, including pancreatic cancer." (PMID 36698109, 2023). "MTHFD2, which comprises this pathway and has two enzymatic activities, dehydrogenase and cyclohydrolase, is reported to be highly expressed at the protein level in a variety of human tumors, including pancreatic cancer, and is negatively correlated with survival." (PMID 36698109, 2023). "In addition, high 1CM activity has been linked to increased tumor aggressiveness and reduced prognosis in several cancer entities, and a dependency of MTHFD2 on KRAS and its prognostic impact was described in AC, colorectal, and pancreatic cancer." (PMID 35888776, 2022). "In addition, the activated human effector T cell induced more severe cell death in MTHFD2-KO SW1990 cells, and an antigen-specific cytotoxicity assay between activated splenocytes from OT-1 mice and mouse pancreatic cancer OVA-Pan02 cells also showed an increased cell death in MTHFD2-KD Pan02 cells." (PMID 33782411, 2021).
liver cancer (4 papers, 2013 to 2022). An epithelial or non-epithelial malignant neoplasm that arises from the liver. "To define its clinical relevance, we queried the TCGA database and found that high MTHFD2 mRNA is significantly correlated with poor prognosis in pancreatic, kidney, lung, breast, and liver cancer patients." (PMID 33782411, 2021).
melanoma (4 papers, 2015 to 2024). A malignant, usually aggressive tumor composed of atypical, neoplastic melanocytes. "Taken together, our data indicated that MTR loss combined with MTHFD2 upregulation led to one-carbon unit enrichment and contributed to PRKDC-MXD3/S57-induced melanoma tumor growth." (PMID 39039072, 2024). "By immunohistochemical staining for MTHFD2, we found nuclear-positive cells in a subset of breast tumor and melanoma cells." (PMID 26461067, 2015). "In this research, we further distinguished 5 differentially expressed UPRRGs (KDELR3, EIF4EBP1, TARS, MTHFD2 and SHC1), which also highly expressed in melanoma at the protein level." (PMID 33136551, 2020). "These genes contained KDELR3, EIF4EBP1, TARS, MTHFD2, SHC1 which all highly expressed in melanoma compared to normal skin in The Human Protein Atlas." (PMID 33136551, 2020).
non-small cell lung carcinoma (4 papers, 2017 to 2022). A group of at least three distinct histological types of lung cancer, including non-small cell squamous cell carcinoma, adenocarcinoma, and large cell carcinoma. "For example, it is shown that common KRAS mutation associates with increased expression of MTHFD2 in non-small cell lung cancer cell lines, while mTORC1-dependent induction of MTHFD2 is reported in both normal and cancer cells." (PMID 29312889, 2017). "The expression and function of MTHFD2 in non-small-cell lung cancer (NSCLC) has also been widely reported." (PMID 36051358, 2022). "Methylenetetrahydrofolate dehydrogenase 2 (MTHFD2) has been reported to be overexpressed in non-small-cell lung cancer (NSCLC) and to correlate with malignant proliferation." (PMID 36051358, 2022).
esophageal cancer (3 papers, 2022 to 2024). A primary or metastatic malignant neoplasm involving the esophagus. "However, and according to our data, there are no studies describing the methylation of these genes in other tumors, with the exception of one publication describing the hypermethylation of CELF6 in oral squamous cell carcinoma and that of MTHFD2 in esophageal carcinoma." (PMID 39305372, 2024).
renal carcinoma (3 papers, 2021 to 2024). A carcinoma arising from the epithelium of the renal parenchyma or the renal pelvis. "The first reported link between MTHFD2 and epigenetics was the discovery that MTHFD2 can promote the methylation of HIF2A mRNA in renal cancer cells to promote aerobic glycolysis." (PMID 40604332, 2024). "Although MTHDF2 is still not clearly defined as a methyltransferase of m6A, MTHFD2 expression is significantly elevated in renal cancer cells and regulates the level of m6A methylation." (PMID 38117350, 2023).
atherosclerosis (2 papers, 2018 to 2025). A disease characterized by the build-up of fatty material and calcium deposition in the arterial wall resulting in partial or complete occlusion of the arterial lumen. "Specifically, MTHFD2 enzyme deficiency significantly suppresses Tfh cell differentiation and delays atherosclerosis progression, suggesting that targeting this pathway may offer a new interventional strategy." (PMID 41562048, 2025). "Thus, we propose that endothelial cells undergo MTHFD2-mediated reprogramming toward serine-glycine and mitochondrial one-carbon metabolism to compensate for the loss of ATP in response to oxPAPC during atherosclerosis." (PMID 29895827, 2018). "Taken together, these data support the notion that MTHFD2 is expressed and upregulated in human atherosclerosis and seems to affect the amino acid glycine and serine metabolism." (PMID 29895827, 2018). "The majority of the MTHFD2 network genes that were induced in response to oxPAPC were also increased in atherosclerosis." (PMID 29895827, 2018). "Expression changes of the MTHFD2 network genes in the carotid arteries in response to atherosclerosis were similar to those of endothelial cells in response to oxPAPC." (PMID 29895827, 2018). "Developing inhibitors or agonists for key molecules such as NLRP3 inflammasome, ALKBH5, MTHFD2, or specific immunoproteasome subunits could lead to novel immune-based strategies for atherosclerosis, offering more precise and effective clinical treatments." (PMID 41562048, 2025). "Since atherosclerosis is driven in part by oxidized lipids, we hypothesized that the MTHFD2 network is active in human atherosclerotic samples." (PMID 29895827, 2018). "Based on this, a key role of MTHFD2 in angiogenesis as well as human atherosclerosis and CAD development could be inferred." (PMID 29895827, 2018). "Although these data link MTHFD2 to the development of atherosclerosis, they must not raise the impression that this response is mediated through oxPAPC." (PMID 29895827, 2018).
bladder urothelial carcinoma (2 papers, 2022 to 2023). "However, the function of MTHFD2 in urothelial carcinomas of bladder (UCB) and its association with tumor immune infiltration remains unknown." (PMID 35581573, 2022). "We observed that MTHFD2 expression level is associated with the tumor microenvironment (TME) in BLCA and has the ability to precisely predict the molecular subtypes, inflamed TME, and immunotherapy response in bladder urothelial carcinoma." (PMID 38130721, 2023).
colorectal tumor (2 papers, 2020 to 2025). "Our findings demonstrate that acetyllysine 88 impaired the enzyme activity of MTHFD2 to restraining cellular redox balance in human colorectal tumor cells." (PMID 32811824, 2020). "Together, these results indicate that K88 acetylation of MTHFD2 is downregulated in colorectal tumors and is correlated with highly expressed SIRT3." (PMID 32811824, 2020). "Expression of the mitochondrial folate metabolism enzymes SHMT2, MTHFD2, and ALDH1L2 was upregulated in colorectal tumor tissues, and their high expression correlated with poor patient prognosis." (PMID 41154660, 2025). "Thus, K88 acetylation of MTHFD2, MTHFD2 protein and SIRT3 may be potential screening biomarkers for human colorectal tumors." (PMID 32811824, 2020).
congenital heart disease (2 papers, 2023 to 2024). A heart disease that is present at birth. "Given the disparity in baseline characteristics between the case and control groups, adjustments were made to investigate the impact of maternal FAS, progeny MTHFD1, and MTHFD2 gene polymorphisms, along with their interactions, on congenital heart disease." (PMID 37630697, 2023). "Variants in the MTHFD1 and MTHFD2 genes associated with congenital heart disease in humans." (PMID 39062651, 2024).
endometrial carcinoma (2 papers, 2023 to 2026). A malignant tumor arising from the epithelium that lines the cavity of the uterine body. "To further evaluate the MTHFD2 protein level, we applied HPA, and results also indicated that MTHFD2 was up-regulated in endometrial carcinoma." (PMID 37484807, 2023). "Additionally, three genes—MRPL15, MTFR2, and MTHFD2—were found functionally linked to MRS2, and their upregulation is associated with unfavorable outcomes in endometrial cancer patients." (PMID 41551444, 2026).
gastric tumor (2 papers, 2020 to 2024). "Expectedly, gene set enrichment analysis (GSEA) revealed the enrichment of ROS-related signature in gastric tumors with high expression of MTHFD2 (normalized enrichment score = 1.73, p = 0.002), demonstrating its critical role in redox homeostasis." (PMID 38723197, 2024). "We found that MTHFD2 expression is higher in gastric tumor tissues and cancer cell lines, and demonstrated that MTHFD2 silencing inhibits growth, arrests the cell cycle at G1/G0, and induces the apoptosis of gastric cells." (PMID 33168819, 2020).
head and neck squamous cell carcinoma (2 papers, 2020 to 2023). A squamous cell carcinoma that arises from any of the following anatomic sites: lip and oral cavity, nasal cavity, paranasal sinuses, pharynx, larynx, and salivary glands. "The aim of this study was to determine the clinical significance of the candidate immune-related metabolic enzymes (IRMEs) methylenetetrahydrofolate dehydrogenase (NADP+ dependent) 2 (MTHFD2) in head and neck squamous cell carcinoma (HNSCC)." (PMID 32933024, 2020). "In head and neck squamous cell carcinoma (HNSCC), low expression of miR-99a-3p, which targets MTHFD2, significantly predicts poor prognosis." (PMID 37147729, 2023).
lung fibrosis (2 papers, 2023). "We thus treated mice with DS18561882 to determine if MTHFD2 inhibition can therapeutically inhibit progression of lung fibrosis after bleomycin instillation." (PMID 37986788, 2023). "Folate supplementation elevated the expression of MTHFD2 and SLC25A32, alleviated oxidative stress and effectively suppressed myofibroblast formation and silica-induced pulmonary fibrosis in mice." (PMID 37280614, 2023). "Folate supplementation elevated the expression of MTHFD2 and SLC25A32, alleviated oxidative stress and effectively suppressed myofibroblast differentiation and silica-induced pulmonary fibrosis in mice." (PMID 37280614, 2023). "Importantly, folate supplementation elevated the expression of MTHFD2 and SLC25A32, suppressed TGF-β induced oxidative stress and effectively mitigated myofibroblast formation and silica-induced pulmonary fibrosis in mice." (PMID 37280614, 2023).
lymph node metastasis (2 papers, 2024). "Higher expression levels of SLC1A5 or MTHFD2 were associated with poorer OS and relapse-free survival (RFS), advanced tumor stages, and increased likelihood of lymph node metastasis in KIRC patients." (PMID 39958609, 2024). "Similarly, high expression of SHMT2 and MTHFD2 was significantly associated with extrathyroidal extension (ETE), lymph node metastasis, stage III or IV, and the presence of the BRAFV600E mutation in the TCGA cohort." (PMID 38331894, 2024).
lymphoma (2 papers, 2013 to 2022). A malignant (clonal) proliferation of B- lymphocytes or T- lymphocytes which involves the lymph nodes, bone marrow and/or extranodal sites. "Comparison of mRNA levels between normal human tissues indicated that MTHFD2 is highly expressed in blood myeloid cells as well as in hematopoietic and mesenchymal stem cells whereas among human malignancies, lymphoma and neuroblastoma showed the highest expression." (PMID 23295955, 2013). "The results indicated that in normal tissues MTHFD2 is expressed especially in blood myeloid cells as well as in hematopoietic and mesenchymal stem cells whereas in cancer samples, the highest expression was seen in lymphoma and neuroblastoma." (PMID 23295955, 2013).